OR5C1 (olfactory receptor family 5 subfamily C member 1)
Description:
Odorant receptor.
Synonyms: OR9-F; OR5C2P; hRPK-465_F_21; OR9-31
Tractability: Antibody: UniProt places it where antibodies can reach, with medium confidence; UniProt predicts a signal peptide or a membrane-spanning region; its Gene Ontology location is reachable by antibodies, with medium confidence.
Gene: Protein-coding gene on chromosome 9 (122,788,933 to 122,789,895, forward strand). Ensembl gene ENSG00000148215.
Subcellular location: Cell membrane
Pathways (Reactome):
Sensory Perception: Expression and translocation of olfactory receptors
Gene Ontology:
Molecular function: odorant binding; olfactory receptor activity; G protein-coupled receptor activity
Biological process: sensory perception of smell; detection of chemical stimulus involved in sensory perception of smell; G protein-coupled receptor signaling pathway
Cellular component: plasma membrane; membrane
Genetic constraint (gnomAD): Loss-of-function variants: 2 observed, 0.71 expected, observed/expected ratio (o/e) 2.81. That is too few expected variants to judge how well the gene tolerates losing a copy. Missense variants: 433 observed, 446.77 expected, observed/expected ratio (o/e) 0.97, 90% interval 0.89 to 1.05. Synonymous variants: 184 observed, 188.19 expected, observed/expected ratio (o/e) 0.98, 90% interval 0.87 to 1.11.
Homologues: Orthologues: chimpanzee OR5C1 (98% identical), macaque OR5C1 (93% identical), rabbit OR5C1 (86% identical), rat Or5c1 (85% identical), dog OR5C1 (85% identical), guinea pig OR5C1 (85% identical), mouse Or5c1 (85% identical), pig OR5C1 (82% identical). Paralogues in human: OR5AR1 (54% identical), OR5W2 (53% identical), OR5J2 (51% identical), OR5B12 (51% identical), OR5B21 (51% identical), OR5AS1 (50% identical), OR5F1 (50% identical), OR8U3 (50% identical), OR5I1 (50% identical), OR8U1 (50% identical), OR9I1 (50% identical), OR8D1 (49% identical), and 84 more.